MYC (MYC proto-oncogene, bHLH transcription factor)
Diseases named in the same sentence as MYC in open-access papers (continued):
Sharing a sentence is not in itself a finding about the gene and the disease.
neuroblastoma (continued). "Together, these findings suggest that ML327 is a novel chemical probe that blocks MYC expression in neuroblastomas and may represent a lead compound for further development of novel therapeutics for this aggressive pediatric solid tumor." (PMID 29207623, 2017). "Interestingly, in tumors with MYC or MYCN overexpression, glycolysis is less important as compared to glutaminolysis in keeping the energy status and for survival, as has been reported in MYCN amplified neuroblastoma cells as well as in MYC-inducible B-cells." (PMID 28430666, 2017). "In addition, MYC-mediated cell death that occurs upon glutamine deprivation of neuroblastoma cells has been shown to be facilitated by the ATF4 pathway." (PMID 28950000, 2017). "Furthermore, both N-MYC and c-MYC were found to upregulate HDAC2 expression in neuroblastoma and pancreatic cancer, respectively, which contributed to MYC-induced tumor cell proliferation and blocked apoptosis in these models." (PMID 28505071, 2017). "We also sought to determine whether RNA interference of MYC was sufficient for the induction of epithelial differentiation in neuroblastoma." (PMID 29207623, 2017). "We validated our protocols in a panel of 15 neuroblastoma cell lines and 2 MYC-amplified non-neuroblastoma cell lines to control for assay specificity, and reveal evidence for different MYCN or ALK status than previously reported for 7 cell lines commonly used in research." (PMID 29156716, 2017). "Amplification of MYCN or constitutive up-regulation of MYC protein is observed in approximately half of high-risk tumors; our findings indicate a novel role of TAMs as inducers of MYC expression in neuroblastomas lacking independent oncogene activation." (PMID 29207662, 2017). "This hypothesis-driven systems bioinformatics work offered novel insights into the PRC2-mediated tumor cell growth and differentiation in neuroblastoma, which may exert oncogenic effects together with MYC regulation." (PMID 28984200, 2017). "Oncogenic expression of MYC proteins is common in adult cancers and also occurs in neuroblastoma, medulloblastoma, rhabdomyosarcoma and retinoblastoma, four common pediatric solid tumors that together account for a major fraction of death from relapsed cancer in children." (PMID 27438153, 2016). "Importantly, like c-Myc, the specific form of MYC in neuroblastoma, N-Myc, also enhances rates of ribosome biogenesis." (PMID 26728659, 2016). "and since c-MYC and MYCN proteins share extensive structural and functional similarities we sought to determine whether LSD1 and MYCN can be associated in Neuroblastoma cells where MYCN is critical to the oncogenic process." (PMID 26062444, 2015). "To prioritize druggable genes and reduce the number of candidates to a manageable number, we used the following criteria: (a) the genes are, or have the potential to be, direct MYC targets; (b) the genes have prognostic value in neuroblastoma; and (c) inhibitors are readily available." (PMID 25477524, 2015). "Moreover, strong overexpression of MYC involved in a “chromothripsis” region was also detected in a neuroblastoma sample." (PMID 24476156, 2014). "Let-7e has been shown to inhibit neuroblastoma proliferation by targeting the MYC oncogene." (PMID 24438171, 2014). "We speculated that down-regulation of MYC was related with N-myc amplification in Y79 cells as in neuroblastoma." (PMID 25359779, 2014). "More specifically, we show here that a significant proportion of such focal copy number changes target genes implicated in MYCN signaling and may therefore reinforce the oncogenic effect of MYCN (or MYC) on neuroblastoma cells." (PMID 23308108, 2013). "Whether this effect is due to the cellular context in which they are expressed and/or due to different functions of the two MYC proteins in neuroblastoma cells is unclear." (PMID 18851746, 2008).
neuroblastoma (continued). "In neuroblastoma – an embryonal tumor with biological similarities to MB – the quassinoid NBT-272 has been demonstrated not only to inhibit cellular proliferation but also to down-regulate c-MYC protein expression." (PMID 17254356, 2007). "Thus, improving NK–NK-mediated cancer killing for MYC–driven neuroblastoma is attractive." (PMID 40962798, 2025). "Therefore, to characterize the influence of WDR5 and PDPK1 on mitotic gene expression in cells with high MYC levels, we performed a comparative transcriptomic analysis in neuroblastoma cell lines defined by MYCN-amplification, which results in high cellular levels of the N-MYC protein." (PMID 38605297, 2024). "IGF2BP3 promotes the stability and storage of its target gene MYC mRNA in a m6A-dependent manner under normal and stress conditions, thereby affecting gene expression output and promoting the occurrence and development of cancer, such as neuroblastoma and nasopharyngeal carcinoma 33-35." (PMID 38577615, 2024). "A latest study revealed that MYC could inhibit tumor immunity in neuroblastoma and melanoma." (PMID 37874682, 2023). "More than 40% of high-risk neuroblastoma (NB) cases are characterized by aberrations in the transcription factors MYCN and c-MYC." (PMID 37760568, 2023). "MYCN activates canonical MYC targets involved in ribosome biogenesis, protein synthesis and represses neuronal differentiation genes to drive oncogenesis in neuroblastoma (NB)." (PMID 37781575, 2023). "Therefore, inhibition of rRNA gene transcription and protein translation by small molecule inhibitors could represent potential therapeutic approaches for MYC-driven neuroblastomas." (PMID 35053227, 2022). "DpC could thus be a useful addition in the treatment of MYC-driven neuroblastomas." (PMID 35008802, 2021). "Therefore, direct inhibition of c-MYC in SH-SY5Y cells would not only further confirm the functional overlap in MYC proteins but also further establish their role in lipid accumulation in neuroblastoma." (PMID 35008802, 2021). "Alternatively, these genes could be synthetically lethal with MYC activation in neuroblastoma." (PMID 34788094, 2021). "The dependence of MYC-driven cancers on components of the spliceosome and the presence of splicing abnormalities in MYC-driven neuroblastoma raise the possibility that splicing factors could be effective targets in neuroblastoma." (PMID 34788094, 2021). "Vitally, even mutant RAS cloned from tumor tissue requires concurrent MYC overexpression for transformation to proceed, highlighting the importance of cooperation between MYCN amplification and oncogenic RAS mutations or activation of RAS-related pathways in neuroblastomas." (PMID 34069817, 2021). "Moreover, alterations to MYC expression and function are found in multiple malignancies, including cancers of the central and peripheral nervous system such as glioblastoma multiforme, and neuroblastoma (NB)." (PMID 34445233, 2021). "Hence, it remains to be elucidated whether the potential regulation of FA metabolism by MYCN in neuroblastoma is different from the MYC regulation in other tumor types." (PMID 31856871, 2019). "Furthermore, deregulated Wnt has been suggested to drive the over-expression of MYC in non-MYCN amplified (non-MNA) high-risk neuroblastomas." (PMID 29505958, 2018). "Our findings that high levels of expression of PRPS2, SDC1 and also SLC7A6 are associated with poor clinical outcome in neuroblastoma, and that PRPS2 and SDC1 are important in proliferation, suggest that these genes may facilitate tumor progression in MYC- and MYCN-driven cancers." (PMID 27448979, 2016).
neuroblastoma (continued). "Therefore, our observations in neuroblastoma cell lines differ from previous observations in hematologic cancer cell lines, where MYC suppression was consistently observed in the context of native, translocated, and amplified loci from a number of different tumor types." (PMID 24009722, 2013). "Neuroblastoma cells have been treated with alisertib, a specific AURKA inhibitor, and were shown to inhibit cell growth, G2/M arrest, degradation of MYC and tumor growth inhibition." (PMID 40104501, 2025). "Both c-MYC and n-MYC require active polyamine synthesis for the formation of lymphomas and neuroblastomas, respectively." (PMID 40444051, 2025). "MYCN belongs to the MYC oncogene family, which consists of three members (MYC, MYCN, and MYCL) and was first identified in neuroblastoma." (PMID 40862719, 2025). "The let-7 miR family plays a crucial role in suppressing neuroblastoma tumors by targeting several oncogenes (DICER1, ARID3B, MYC, HMGA2)." (PMID 40104501, 2025). "Neuroblastoma cell lines (SH-SY5Y and SK-N-AS and BL cell lines (WEHI-47 and KOPN-8), characterized by high c-MYC expression, were treated with increasing concentrations of WS6 (0–2 μM)." (PMID 41002386, 2025). "Our analysis suggests that ATP13A3 is a MYC target gene like ODC1 and SLC3A2 and that high expression of ATP13A3 represents an independent prognostic predictor of poor outcome in neuroblastoma." (PMID 39981745, 2025). "The enrichment of MYC-target gene products is of particular interest, as MYCN and C-MYC play important roles in the pathophysiology of neuroblastoma." (PMID 39767807, 2024). "To assess this possibility, we knocked down JMJD6 in neuroblastoma cell lines BE2(C) and SK-N-AS, which express MYCN and MYC, respectively, for RNA-seq analysis." (PMID 38488852, 2024). "Lastly, we validated that JMJD6 is essential to neuroblastoma growth in MYCN-amplified (BE2C) and MYC-overexpressed (SK-N-AS) xenograft models." (PMID 38488852, 2024). "Analysis of human neuroblastoma tumor cohorts showed a strong correlation between dysregulated mitosis and features of MYCN amplification, such as MYC(N) transcriptional activity, poor overall survival, and other clinical predictors of aggressive disease." (PMID 37958555, 2023). "In line with this reasoning, activation of the ISR by thapsigargin was also sufficient to downregulate c-MYC, HIF-1α, and MCL-1 in neuroblastoma cells already within 1 h of treatment, whereas BCL-2 levels remained unchanged." (PMID 37973789, 2023). "Here, we focus on N-MYC amplified neuroblastoma to determine the extent of colocalization between N-MYC and WDR5 on chromatin while also demonstrating that like c-MYC, WDR5 can facilitate the recruitment of N-MYC to conserved WDR5-bound genes." (PMID 37336886, 2023). "Survival of patients with MYC family‐driven neuroblastomas in which tumors were n‐MYC‐ and/or c‐MYC‐positive was significantly worse than that of patients without non‐MYC family‐driven tumors." (PMID 36694106, 2023). "We found that MYC and MYCL were enriched in high-NE-score SCLC lines, whereas MYCN amplification was enriched in high-NE-score neuroblastoma lines." (PMID 37255415, 2023). "This is in line with previously published data showing increased sensitivity of cancer cells with high MYC/MYCN-expression to PARPi including glioblastoma stem-like cells, neuroblastoma, multiple myeloma and medulloblastoma cells in vivo and in vitro." (PMID 37783879, 2023). "Using neuroblastoma and small cell lung carcinoma as model systems, we herein identify a previously underappreciated crosstalk between EZH2 and MYC(N) in regulation of tumor formation." (PMID 35013218, 2022). "The effect of MYC family proteins on HLA generalizes to other cancers as well, as MYC and MYCN can suppress HLA-I in melanoma and neuroblastoma, respectively." (PMID 35775490, 2022).
neuroblastoma (continued). "As such, combining PBNP-PTT with MYC targeting via drugs such as I-BET726 or JQ1 in MYCN-amplified neuroblastoma cells may generate immunogenicity more similar to that seen in SH-SY5Y cells, and may provide effective treatment for high-risk neuroblastoma patients with MYCN amplification." (PMID 35326601, 2022). "For example, the oncoprotein MYC in T-cell leukemia is directly acetylated, while acetylation through histone H3K9 also indirectly elevated MYC transcription in neuroblastoma cells and hepatocarcinoma." (PMID 36226054, 2022). "Downregulation of MYC or MYCN protein expression upon MYCMI-7 treatment was also confirmed in HeLa, P493-6, HCT116 cells, and in MYCN-amplified Kelly neuroblastoma cells." (PMID 36874405, 2022). "The effects of PPRHs were examined in an array of MYC-overexpressing and -addicted cell lines, including estrogen receptor-positive breast MCF-7, neuroblastoma SH-Sy5y, colorectal SW480, and prostate PC-3 cancer cells." (PMID 36613820, 2022). "Consistent with their higher sensitivity to ferroptosis, MYCN-amplified neuroblastoma cells had lower baseline GSH and cysteine levels compared to cell lines with lower MYC(N) activity scores." (PMID 35484422, 2022). "Similar results were obtained in MYC-driven SK-N-AS cells, supporting that EZH2 globally sustains MYC(N) protein stability in neuroblastoma cells." (PMID 35013218, 2022). "The PPRHs designed demonstrated broad and potent efficacy in MYC-addicted or overexpressing colorectal (SW480), neuroblastoma (SH-Sy5y), breast (MCF-7), prostate (PC-3), and pancreatic cancer cells (AsPc-1)." (PMID 36613820, 2022). "Here, the authors use neuroblastoma and small cell lung carcinoma model systems and reveal the crosstalk between EZH2 and MYC(N) in the regulation of tumour formation." (PMID 35013218, 2022). "The consequence of HSP90 inhibition on neuroblastoma cells, both IMR-32 and SK-N-AS, was growth suppression and a decrease in MYC or MYCN expression." (PMID 36185250, 2022). "Subsequently, two MYC paralogues, MYCN (initially identified in neuroblastomas) and MYCL, were cloned in neuroblastoma and lung cancers, respectively." (PMID 34201047, 2021). "In a syngeneic mouse model of neuroblastoma (TH-MYCN), c-MYC expression is detected in stromal cells surrounding nests of MYCN-positive neuroblastomas." (PMID 34847775, 2021). "In MYC-driven medulloblastoma models, OTX015 IC50 between 142.6 nM and 448.6 nM have been reported, while in MYCN-driven neuroblastoma, IC50s span from 37 nmol/L to >1 μmol/L." (PMID 33668642, 2021). "In MYC-amplified neuroblastoma cells, n-MYC and c-MYC bind to the proximal DKC1 promoter and drive the expression of DKC1 gene." (PMID 33599797, 2021). "We determined the mRNA copy levels of MYC and MYCN in SU-DIPGVI and HSJD-DIPG007 and found low copy numbers of both genes in comparison to known amplified neuroblastoma cultures (SJ-G2 and BE2C)." (PMID 33579942, 2021). "To investigate the functional and clinical significance of these dysregulated genes, we extracted gene expression data of the paediatric neuroblastoma patients from TARGET study (2018, n=1,089 patients) and checked their co-expression with MYC members." (PMID 32483461, 2020). "As in the PDAC context, where MYC directly activates the transcription of the pro‐death BCL2 family member NOXA (PMAIP1) upon bortezomib treatment, NOXA contributes also in neuroblastoma models significantly to the bortezomib‐induced apoptosis." (PMID 33099868, 2020). "Neuroblastoma tumours have been shown to express high levels of SKP29 and c-MYC upregulates SKP2 expression." (PMID 31900399, 2020). "Despite the importance of the MDM2-MYCN axis in neuroblastoma and retinoblastoma, it has been unclear if MDM2 promotes MYCN expression in additional cancers and if MDM2 also regulates MYC." (PMID 33425720, 2020).
neuroblastoma (continued). "Further studies have additionally shown that in neuroblastoma cells MYCN targets a separate E-box location and, similarly to c-MYC, augments transcription of SKP211." (PMID 31900399, 2020). "Except MYC, transcription factor E2F1 was also positively enriched in MYCN amplified neuroblastoma tissues in GSE19274 and GSE85047 datasets." (PMID 32593299, 2020). "MYC, E2F1 transcription factors and ribosome signaling pathway were significantly enriched in neuroblastoma patients with MYCN amplification." (PMID 32593299, 2020). "The application of inhibitors that target multiple CDKs, including CDK12, led to the downregulation of N-MYC and c-MYC and their transcription programmes in MYC-driven neuroblastoma and ovarian cell lines, respectively." (PMID 34316683, 2020). "Past studies showed that MYCN upregulates MDM2 RNA in neuroblastoma cells by binding to MDM2 promoter E-box sequences, and we here corroborate that ectopic MYCN upregulates MDM2 in MYC-expressing SH-SY5Y." (PMID 33425720, 2020). "In neuroblastoma primary tumors with low MYCN, tumors with high c-MYC protein had a trend of higher MK2 protein expression relative to those with low MYCN and c-MYC proteins." (PMID 32409685, 2020). "Previous studies in neuroblastoma and glioblastoma have demonstrated that PRMT5 can physically interact with MYC and regulate its stability at the post-translational level." (PMID 31694585, 2019). "In conclusion, this report is the first to identify miR-665 as a potent tumor suppressor that directly targets the 3’-UTRs of HDAC8, c-MYC, and MYCN, each of which is involved in neuroblastoma tumorigenesis." (PMID 30237861, 2018). "In contrast to GU, the MYC gene family expression was limited to MYCN, a feature shared with neuroblastomas." (PMID 29487377, 2018). "Specific inhibition of hyperactive rRNA synthesis and protein translation was shown to be an effective way to suppress MYC/MYCN protein expression and neuroblastoma growth." (PMID 29464082, 2018). "Assessing the regulation of TFAP4 by MYCN/MYC, we found that high TFAP4 expression correlates with high MYCN or MYC expression in neuroblastoma cell lines and in the TARGET cohort of patients." (PMID 29880876, 2018). "Our laboratory is presently investigating the therapeutic effects of miR-665 and c-MYC- and HDAC8-specific siRNAs in transplanted mouse neuroblastoma tumors." (PMID 30237861, 2018). "To determine the mechanism by which miR-665 inhibited neuroblastoma cell proliferation, we investigated the effects of miR-665 on HDAC8 and c-MYC expression." (PMID 30237861, 2018). "This is the first report demonstrating that miR-665 is a suppressor miRNA targeting both c-MYC and HDAC8, which are involved in neuroblastoma tumorigenesis." (PMID 30237861, 2018). "Bt2cAMP also upregulated miR-665, and miR665 transfection mimicked the effects of Bt2cAMP, including reduced c-MYC and HDAC8 expression, increased caspase 3 activation, and reduced neuroblastoma cell growth." (PMID 30237861, 2018). "Our study, for the first time, showed that Halofuginone effectively down-regulated MYC and MYCN proteins in MYC family driven neuroblastoma cells." (PMID 29464082, 2018). "As expected, the vast majority (103/120, 85.8%) of MYCN amplified High-MKI neuroblastomas overly expressed MYCN protein, including 2 tumors also having simultaneous MYCN and MYC protein expression." (PMID 29464082, 2018). "We found that miR-665 suppresses mRNAs, targeting c-MYC and HDAC8, which are involved in neuroblastoma tumorigenesis." (PMID 30237861, 2018). "Particularly, the transcription of MYCN was comparable in tumor and DTC samples, as well as the transcription of MYC, which was earlier shown to be anti‐correlated with MYCN in neuroblastoma." (PMID 28921546, 2018).